GAS5 (growth arrest specific 5)
Diseases named in the same sentence as GAS5 in open-access papers (continued):
Sharing a sentence is not in itself a finding about the gene and the disease.
breast carcinoma (continued). "The functions of GAS5 in breast cancer are well established in apoptosis (both spontaneous and induced by chemotherapy)." (PMID 34202777, 2021). "Aberrant GAS5 expression has been detected in several cancers, including breast cancer, 17 and gastric cancer." (PMID 33391419, 2021). "In breast cancer, miR-221 is the target of GAS5, and GAS5 regulates DKK2 expression by competitively binding miR-221-3p, inhibiting the activation of Wnt / β-Catenin pathway, enhancing the anti-tumor effect of adriamycin." (PMID 34022918, 2021). "In future studies, the role of GAS5 in other breast cancer processes should be studied in more detail." (PMID 34202777, 2021). "The expression of GAS5 is increased by mTOR inhibitors, which are now widely used in clinical practice and have been proposed to improve the responses to chemotherapy in breast cancer." (PMID 34202777, 2021). "Larger tumor volume, advanced lymph node metastasis, and estrogen receptor negativity in breast cancer cells are the outcomes of GAS5 downregulation." (PMID 34527584, 2021). "GAS5 is also a key player in the regulation of some crucial signal pathways in breast cancer, such as PI3K/AKT/mTOR, Wnt/β-catenin, and NF-κB signaling." (PMID 34202777, 2021). "The mutual inhibitory effect of GAS5 and miR-21was revealed in experiments on the transfection of breast cancer cell lines." (PMID 34202777, 2021). "Many studies have addressed the effect of GAS5 in breast cancer on apoptosis and sensitivity to chemotherapy." (PMID 34202777, 2021). "The dual-luciferase reporter and RIP assays confirmed the direct binding between miR-221-3p and GAS5 in MCF-7/ADR breast cancer cells." (PMID 34202777, 2021). "Only one study provided evidence that GAS5 knockdown induces epithelial-mesenchymal transition in breast cancer cells in vitro." (PMID 34202777, 2021). "In breast cancer, GAS5 participates in the activation of proteins that include PTEN, PDCD4, DKK2, FOXO1, and SUFU through a ceRNA mechanism mediated by various miRNAs, including miR-21, miR-222, miR-221-3p, miR-196a-5p, and miR-378a-5p." (PMID 34202777, 2021). "GAS5 is a well-studied down regulated lncRNA in breast cancer while GLRX2 is a protein that localizes to the mitochondria where it functions in mitochondrial redox homeostasis and is important for the protection against and recovery from oxidative stress." (PMID 34717732, 2021). "In this way, a new axis of interactions for lncRNA GAS5 in breast cancer was revealed: GAS5/miR-222/PTEN." (PMID 34202777, 2021). "GAS5 levels were decreased in breast cancer cell lines—most significantly in TNBC cell lines MDA-MB-231 and MDA-MB-468." (PMID 34202777, 2021). "There is no doubt that methylation of the promoter CpG island is at least partly involved in the downregulation of GAS5 gene expression in various cancers, including breast cancer." (PMID 34202777, 2021). "In breast cancer, GAS5 binds with miR-21, miR-222, miR-221-3p, miR-196a-5p, and miR-378a-5p that indicates the presence of several elements for miRNA binding (MREs) in GAS5." (PMID 34202777, 2021). "GAS5 can stimulate apoptosis in breast cancer via diverse pathways, including cell death receptors and mitochondrial signaling pathways." (PMID 34202777, 2021). "Given that GAS5 enhances apoptosis and inhibits breast cancer cell proliferation, the same study assessed the effect of GAS5 on apoptosis and cell proliferation in TNBC cell lines." (PMID 34202777, 2021). "In breast cancer, the expression of GAS5 correlates with the expression of unc-51-like autophagy activating kinases (ULK) 1/2 (the examined collection, unfortunately, did not contain TNBC samples)." (PMID 34202777, 2021). "The growth-arrest specific 5 (GAS5) lncRNA is downregulated in tamoxifen-resistant breast cancer cells, and low GAS5 expression enhances resistance to tamoxifen." (PMID 32486413, 2020).
breast carcinoma (continued). "It has been demonstrated that GAS5 is down-regulated in many cancers, such as breast cancer, hepatocellular carcinoma, lung cancer and ovarian cancer 14-18." (PMID 32547314, 2020). "Another report showed that GAS5 manifested tumor suppressor effects and induced chemosensitivity to breast cancer cells by indirectly targeting the miR-378-5p/SUFU signaling pathway, as well as by competitively binding miR-196a-5p." (PMID 33076450, 2020). "This was also reported in a recent work, which indicated that GAS5 is down-regulated in breast cancer and that it negatively impacts disease prognosis." (PMID 33076450, 2020). "A recent study highlighted the role of GAS5 in breast cancer and adriamycin resistance, through the gene’s interaction with miR-221-3p." (PMID 33076450, 2020). "Related to cell proliferation, GAS5 dysregulation is involved in multiple signaling pathways, all of which correlate with the progression of breast cancer." (PMID 33291485, 2020). "GAS5 suppresses glucocorticoid-induced transcription and sensitizes breast cancer cells to apoptosis." (PMID 32486413, 2020). "To confirm the higher E33 expression in breast cancer induced by diabetes, we selected four LncRNAs (H19, E33, LIPCAR, and GAS5) that have been shown to be associated with diabetes." (PMID 31907990, 2020). "GAS5 is downregulated in multiple cancers and acts a tumor suppressor in breast cancer, prostate cancer, lung adenocarcinoma, and pancreatic cancer." (PMID 33195407, 2020). "GAS5 (growth specific arrest 5), a tumorsuppressor lncRNA in breast cancer was also found to be downregulated in ACC." (PMID 32079166, 2020). "It has been demonstrated that GAS5 is down-regulated in many cancers, such as breast cancer, hepatocellular carcinoma, lung cancer and ovarian cancer 14-17." (PMID 32547314, 2020). "For example, the well-characterized tumor suppressor lncRNA GAS5, which is down-regulated in breast cancer, is a SNHG that has multiple snoRNAs that are processed from its introns." (PMID 32444795, 2020). "While GAS5 expression was low under normal conditions in breast cancer, its expression was significantly upregulated by IDET." (PMID 31784542, 2019). "In line with this tumor suppressor phenotype, plasmid-based overexpression of human GAS5 in the estrogen-dependent breast cancer cell line MCF7 promotes apoptosis and reduces proliferation." (PMID 31533355, 2019). "Previous studies have shown that GAS5 functions as a tumor suppressor by promoting apoptosis in breast cancer and both apoptosis and cell cycle arrest in neuroblastoma." (PMID 30569211, 2019). "The latest studies demonstrated that GAS5 usually functions as a tumour suppressor to control apoptosis of various cancer cells, including breast cancer, prostate cancer, renal cell carcinoma, and ovarian cancer." (PMID 31182053, 2019). "Similar to these observations, downregulation in GAS5 expression decreases the therapeutic effects of dendrosomal curcumin in breast cancer cells." (PMID 31784542, 2019). "GAS5 has been reported as a tumor suppressor in some kinds of cancers, and it has been shown the GAS5 is involved in proliferation, apoptosis, and migration of tumor cells in breast cancer, gastric cancer and prostate cancer." (PMID 30534359, 2018). "A large body of research suggested that Gas5 was dysregulated in multiple cancers, such as prostate cancer and breast cancer and confirmed a tumor suppressor role for this molecule." (PMID 29423063, 2018). "The abnormal down-regulation of lncRNA GAS5 has been observed in various cancers, such as breast cancer, renal cell carcinoma, bladder cancer, prostate cancer, and pancreatic cancer." (PMID 29229673, 2018). "LncRNA growth arrest-specific transcript 5 (GAS5) was found to be consistently down-regulated and acted as a tumor suppress gene in various cancers, such as gastric cancer, prostate, and breast cancer." (PMID 29229673, 2018).
breast carcinoma (continued). "The expression of ZFAS1, like GAS5, is also up-regulated in normal mammary glands compared to breast cancer tissues." (PMID 29416676, 2018). "GAS5 (Growth arrest-specific transcript 5) transcripts regulate both cell death and proliferation and are found to be reduced in both breast cancer and HNSCC compared to normal." (PMID 30577491, 2018). "Emerging evidence have suggested GAS5 as an indicator of overall survival in hepatocellular carcinoma, cervical cancer, gastric cancer, breast cancer, and colorectal cancer." (PMID 28977945, 2017). "GAS5 has been found at different levels of expression in many types of cancer such as non-small cell lung cancer, breast cancer, and gastric cancer." (PMID 28108736, 2017). "Recent studies indicated that GAS5 has been found low expression in many types of tumors including breast cancer, colorectal cancer and prostate cancer, however, their functional significance still needs to be established." (PMID 29296179, 2017). "Low expression of GAS5 was identified in multiple cancers, including breast cancer, prostate cancer, colorectal cancer and lung cancer." (PMID 27732939, 2017). "In addition, downregulation of GAS5 has been associated with chemoresistance in some malignant neoplasms, by affecting the sensitivity to adriamycin in gastric cancer, trastuzumab in breast cancer, mTOR inhibition in prostate cancer, and EGFR tyrosine kinase inhibition in wide-type EGFR NSCLC." (PMID 29029523, 2017). "Toward a better understanding of the mechanistic involvement of GAS5 in trastuzumab-resistant breast cancer cells, they found that knockdown of GAS5 led to cell proliferation and tumor growth in SKBR-3 trastuzumab-resistant cancer cells." (PMID 29299178, 2017). "In 2009, Mourtada-Maarabouni and colleagues reported that GAS5 is downregulated in breast cancer tissues." (PMID 27608009, 2016). "GAS5 lncRNA exerts pro-apoptotic effects in breast cancer cell lines as does the GAS5 HREM DNA oligonucleotide." (PMID 26862727, 2016). "While Growth Arrest-Specific 5 (GAS5) is a tumor suppressor lncRNA and is significantly downregulated in breast cancers, and GAS5 can induce cell apoptosis directly or indirectly in cancer cell lines." (PMID 27660759, 2016). "We transfected si-GAS5 into SKBR-3 breast cancer cells; GAS5 knockdown increased cell proliferation." (PMID 27034004, 2016). "GAS5 lncRNA levels are down-regulated in a wide range of tumours, including breast cancer; in many cancers low levels of expression are prognostic of poor patient survival." (PMID 26862727, 2016). "Endogenous GAS5 lncRNA levels are reduced in breast tumour versus adjacent normal tissue and in hormone-insensitive versus hormone-sensitive breast cancer cells." (PMID 26862727, 2016). "An important question relates to the mechanism of action of the GAS5 HREM oligonucleotide in promoting the apoptosis of breast cancer cells." (PMID 26862727, 2016). "GAS5 lncRNA has previously been shown to induce apoptosis in hormone-insensitive breast cancer cells in addition to hormone-sensitive cell lines." (PMID 26862727, 2016). "This preclinical study aimed to determine if the GAS5 HREM sequence alone promotes the apoptosis of breast cancer cells." (PMID 26862727, 2016). "The results of Real-time PCR analysis showed that GAS5 expression was significantly downregulated in trastuzumab-resistant patients with breast cancer." (PMID 27034004, 2016). "At the cellular level, GAS5 lncRNA promotes growth arrest and/or apoptosis of multiple cell types, including hormone-sensitive and –insensitive breast cancer cells, which is likely to account for its tumour suppressor function." (PMID 26862727, 2016). "In hormone-sensitive breast cancer cells, siRNA-mediated knockdown of GAS5 lncRNA attenuates responses to a range of pro-apoptotic treatments, including UV-C irradiation." (PMID 26862727, 2016). "Low GAS5 expression in breast cancer patients correlated with histological grading and advanced TNM stage." (PMID 27034004, 2016).
breast carcinoma (continued). "Growth arrest-specific 5 (GAS5) lncRNA promotes apoptosis, and its expression is down-regulated in breast cancer." (PMID 26862727, 2016). "Cellular GAS5 expression suggest a role of GAS5 in the regulation of apoptosis in breast cancer cell lines and tumors and an inverse association with the mTOR expression in PCa cell lines." (PMID 25999983, 2015). "According to the lncRNADisease Database, there are 16 lncRNAs known to play a role in breast cancer including H19, growth arrest-specific 5 (GAS5), homeobox antisense intergenic RNA (HOTAIR), and breast cancer anti-estrogen resistance 4 (BCAR4)." (PMID 25849966, 2015). "GAS5 expression is downregulated in breast cancer samples relative to adjacent unaffected normal breast tissue, and has a distinct tumor suppressive role in breast cancer by inducing apoptosis and suppressing cell proliferation." (PMID 25849966, 2015). "GAS5 has been shown to be aberrantly expressed in prostate cancer, renal cell carcinoma, breast cancer, head and neck squamous cell carcinoma (HNSCC), and glioblastoma multiforme." (PMID 24884417, 2014). "LncRNA expression is de-regulated in many types of cancers, such as HOTAIR in breast tumours and metastases, BACE1-AS in Alzheimer's disease and Gas5 in breast cancer." (PMID 25025236, 2014). "Growth arrest-specific 5 acts as a tumor suppressor gene in breast cancer as its expression is significantly reduced compared to normal breast epithelium." (PMID 25400658, 2014). "The lincRNA GAS5 is a well described tumor suppressor in breast cancer, and very recently it was described in prostate cancer cell lines and in RCC." (PMID 24238219, 2013). "GAS5 can induce apoptosis directly or indirectly in the prostate and breast cancer cell lines, where it was shown that GAS5 has a significantly lower expression in breast cancers compared to normal breast epithelial tissues." (PMID 23443164, 2013). "For example, Growth Arrest-Specific 5 (GAS5) has been observed to be downregulated in breast cancer, perhaps to sensitize cells to apoptosis by regulating the activity of glucocorticoids in response to nutrient starvation." (PMID 23680400, 2013). "Growth arrest specific 5 has previously been reported to be downregulated in breast cancer compared with normal tissue; however, its role in prognosis or in other cancers has not been elucidated." (PMID 21407217, 2011). "Moreover, GAS5 acts as a tumor suppressor in breast cancer through modulation of the PI3K/AKT/mTOR pathway and participation in Wnt/β-catenin signaling." (PMID 39958058, 2025). "It suggests that GAS5 possesses potential as a therapeutic target in breast cancer treatment." (PMID 40142329, 2025). "In contrast, GAS5 shows downregulation in some other types of cancers, such as breast cancer." (PMID 39958058, 2025). "Next, we explored the biological functions of the FTO/GAS5/IGF2BP2/QKI axis in breast cancer." (PMID 38782769, 2024). "In addition, knockdown or overexpression of IGF2BP2 or QKI reversed the effect of GAS5 on the proliferation of breast cancer cells, respectively." (PMID 38782769, 2024). "The role of GAS5-derived snoRNAs in the pathogenesis of various diseases is speculated upon; for instance, SNORD44 is associated with the prognosis of breast cancer or head and neck squamous cell carcinoma." (PMID 39795871, 2024). "Moreover, overexpression or knockdown of FTO affected the inhibitory effect of GAS5 on the proliferation of breast cancer cells." (PMID 38782769, 2024). "Studies in MCF-7R breast cancer cells have shown that upregulation of the lncRNA GAS5 may also contribute to the anti-proliferative effects of metformin." (PMID 38543182, 2024). "We also found that QKI expression was low in breast cancer tissues and positively correlated with GAS5 expression, suggesting that GAS5 may regulate QKI." (PMID 38782769, 2024). "We elucidated that GAS5 suppressed breast cancer growth via IGF2BP2/QKI, and this inhibitory effect could be attenuated by FTO." (PMID 38782769, 2024).
breast carcinoma (continued). "The lncRNA growth arrest-specific 5 (GAS5) is involved in regulating breast cancer progression." (PMID 38782769, 2024). "In this study, we aimed to elucidate the function and mechanism of GAS5 in breast cancer." (PMID 38782769, 2024). "For example, miR-221-3p, a tumour suppressor miRNA in breast cancer, has several conserved binding sites with the lncRNA GAS5, indicating that GAS5 may function as a ceRNA for miR-221-3p." (PMID 39679367, 2024). "QKI, a tumor suppressor that represses breast cancer, was predicted as a possible target of GAS5." (PMID 38782769, 2024). "Finally, we investigated the biological functions of the FTO/GAS5/IGF2BP2/QKI axis in breast cancer." (PMID 38782769, 2024). "Hence, lncRNAs, such as DANCR, HOTAIR, H19, and GAS5, are identified as key regulators of autophagy in breast cancer, and further research needs to be carried out to identify their potential in breast cancer diagnosis and treatment." (PMID 36899946, 2023). "lncRNA GAS5 was negatively modulated by miR-21 in breast cancer." (PMID 36854894, 2023). "The lncRNA GAS5 plays a significant role in tumorigenicity and progression of breast cancer (BC)." (PMID 37444428, 2023). "In addition, GAS5 also plays an important role in regulating chemotherapy resistance in breast cancer, lung cancer, ovarian cancer, and other tumors." (PMID 37993867, 2023). "Meanwhile, down‐regulation of lncRNAs such as NF‐κB interacting lncRNA (NKILA), EPB41L4A antisense RNA 2 (EPB41L4A‐AS2), and Growth arrest‐specific transcript 5 (GAS5) inhibit breast cancer progression and may advance invasion and metastasis of breast cancer." (PMID 36274054, 2023). "Moreover, overexpression of GAS5 resulted in increased G2/M arrest and unrepaired DNA damage, indicating a radiosensitizing role of GAS5 in breast cancer cells." (PMID 35059460, 2022). "In addition to its role in breast cancer, lncRNA GAS5 was also found to have key roles in regulating cell apoptosis and chemoresistance in cervical cancer, liver cancer, and gastric cancer." (PMID 35059460, 2022). "The growth arrest-specific 5 (GAS5) RNA, a long non-coding RNA, has been proven to alter the apoptosis of breast cancer cells, the angiogenesis of colorectal cancer, the tumorigenesis of non-small cell lung cancers, and the expression of insulin receptors in the previous literature." (PMID 35456391, 2022). "Other studies have found that in breast cancer, the expression level of growth rest gene transcript 5 (Gas5) tends to reduce to 34% of those of adjacent normal tissue, while the Gas5 can induce cell apoptosis by regulating the target gene and play the function of tumor suppressor gene." (PMID 36406273, 2022). "In this study, we investigated the effects of lncRNA GAS5 on cellular radiosensitivity and found that GAS5 could be a potential therapeutic target for treating breast cancer combined with IR." (PMID 35059460, 2022). "For example, GAS5 contributes to the development of breast cancer via a ceRNA-dependent mechanism." (PMID 35155450, 2021). "Like a sponge, GAS5 can directly associate with the binding site in miRNA-23a, inactivating the miRNA-23a mimic and counteracting the negative effects of the miRNA-23a mimic on ATG3 to promote autophagy in breast cancer cells." (PMID 35155450, 2021). "Thus, PTEN, the target of a number of miRNAs regulated by GAS5, is an indicator of the invasion and metastasis of breast cancer." (PMID 34202777, 2021). "Furthermore, these data reveal several sites (i.e., MREs) that can bind various miRNAs (miR-21, miR-222, miR-221-3p, miR-196a-5p, and miR-378a-5p) in GAS5 in breast cancer." (PMID 34202777, 2021). "Another negative regulator of GAS5 in breast cancer is Notch-1." (PMID 34202777, 2021).